SCN3A (sodium voltage-gated channel alpha subunit 3)
Description:
Pore-forming subunit of Nav1.3, a voltage-gated sodium (Nav) channel that directly mediates the depolarizing phase of action potentials in excitable membranes. Navs, also called VGSCs (voltage-gated sodium channels) or VDSCs (voltage-dependent sodium channels), operate by switching between closed and open conformations depending on the voltage difference across the membrane. In the open conformation they allow Na(+) ions to selectively pass through the pore, along their electrochemical gradient. The influx of Na+ ions provokes membrane depolarization, initiating the propagation of electrical signals throughout cells and tissues. In some secretory cell types, it also participates in cell excitability through membrane depolarization and regulates cells responsiveness to stimuli triggering secretion. For instance, it controls the release of serotonin/5-hydroxytryptamine by enterochromaffin cells and is required for both glucagon- and glucose-induced insulin secretion in pancreatic endocrine cells (By similarity).
Synonyms: NAC3; Nav1.3; DEE62; EIEE62; FFEVF4
Tractability: Small molecule: an approved drug acts on it; a structure with a bound ligand is known; a high-quality ligand is known; it belongs to a druggable protein family. Antibody: UniProt places it where antibodies can reach, with high confidence; its Gene Ontology location is reachable by antibodies, with high confidence; UniProt predicts a signal peptide or a membrane-spanning region. PROTAC: UniProt records ubiquitination sites on it; ubiquitination databases record sites on it; its protein half-life has been measured; a small molecule that binds it is known.
Target class: Voltage-gated ion channel; Voltage-gated sodium channel; Ion channel
Gene: Protein-coding gene on chromosome 2 (165,087,526 to 165,204,050, reverse strand). Ensembl gene ENSG00000153253.
Subcellular location: Cell membrane; Basal cell membrane
Pathways (Reactome):
Developmental Biology: Interaction between L1 and Ankyrins
Muscle contraction: Phase 0 - rapid depolarisation
Sensory Perception: Sensory perception of sweet, bitter, and umami (glutamate) taste
Gene Ontology:
Molecular function: voltage-gated sodium channel activity; monoatomic cation channel activity; monoatomic ion channel activity
Biological process: membrane depolarization during action potential; cardiac muscle cell action potential involved in contraction; sodium ion transmembrane transport; sodium ion transport; action potential; behavioral response to pain; monoatomic ion transport; transmembrane transport
Cellular component: plasma membrane; voltage-gated sodium channel complex; basal plasma membrane; cytoplasm; membrane
Genetic constraint (gnomAD): Loss-of-function variants: 45 observed, 165.8 expected, observed/expected ratio (o/e) 0.27, 90% interval 0.21 to 0.35. The upper end of that interval is the gene's LOEUF score, 0.35, which puts it in group 1 of 6, group 1 being the genes least tolerant of losing a copy. Missense variants: 1,495 observed, 2,338.7 expected, observed/expected ratio (o/e) 0.64, 90% interval 0.61 to 0.67. Synonymous variants: 728 observed, 806.79 expected, observed/expected ratio (o/e) 0.9, 90% interval 0.85 to 0.96.
Gene-disease validity (ClinGen):
ClinGen rates the evidence that SCN3A causes each of these diseases.
genetic developmental and epileptic encephalopathy (autosomal dominant): Definitive. A complex neurodevelopmental disorder characterized by a range of developmental delays and epileptic encephalopathy phenotypes.
Homologues: Orthologues: chimpanzee SCN3A (99% identical), macaque SCN3A (99% identical), rabbit SCN3A (97% identical), rat Scn3a (97% identical), pig SCN3A (96% identical), guinea pig SCN3A (96% identical), mouse Scn3a (95% identical), dog SCN3A (92% identical). Paralogues in human: SCN2A (88% identical), SCN1A (84% identical), SCN9A (76% identical), SCN8A (75% identical), SCN5A (64% identical), SCN4A (64% identical), SCN10A (56% identical), SCN11A (47% identical), SCN7A (44% identical), CACNA1A (25% identical), CACNA1B (24% identical), CACNA1C (24% identical), and 14 more.
Diseases named in the same sentence as SCN3A in open-access papers:
SCN3A is named in the same sentence as 81 diseases in open-access papers, as found by Europe PMC text mining. Sharing a sentence is not in itself a finding about the gene and the disease. The quoted sentences say what the papers report.
epilepsy (56 papers, 2008 to 2026). A brain disorder characterized by episodes of abnormally increased neuronal discharge resulting in transient episodes of sensory or motor neurological dysfunction, or psychic dysfunction. "SCN3A-related epilepsies are increasingly recognized for their strong association with malformations of cortical development, particularly polymicrogyria." (PMID 41573391, 2025). "Several of the MIA increased placental genes were also associated with various CNS disorders, such as epilepsy (Gnao1 and Scn3a)." (PMID 38715090, 2024). "SCN3A is also considered to be related to neurodevelopmental disorders and epilepsy, and SCN3A pathogenic mutations reflect many phenotypes." (PMID 38174099, 2023). "SCN1A/SCN2A/SCN8A variant-related epilepsy was generally manifested at an earlier age, while the SCN3A/SCN9A/SCN1B variant-related subtype showed a later age at onset." (PMID 38174099, 2023). "A previous study showed that SCN3A, which encodes the voltage-gated sodium channel subunit Nav1.3, caused severe epilepsy and disordered cortical development." (PMID 37627046, 2023). "We found that these variants, rs1965757, rs7581811, rs7592445 rs3943809, rs12614399 of SCN2A and rs7598098 of SCN3A imply variation of epilepsy risk depending on the individuals’ gender." (PMID 35801810, 2022). "The available data that describe the association between SCN3A variants and epilepsy are limited and few were correlated to focal epilepsy." (PMID 35801810, 2022). "Previous reports correlate heterozygous variants in SCN3A in association with moderate forms of epilepsy, while homozygosis is related with severe cognitive damage and premature mortality, resulting in a broad range of epileptic phenotypes." (PMID 33013363, 2020). "No clear function has been assigned to this gene, but it mRNA covaries well (r = 0.72) in mouse hippocampus with a voltage-gated sodium channel (SCN3A) that itself is linked to autism and epilepsy." (PMID 24523945, 2014). "Currently, there are thirteen reported variants of SCN3A implicated in epilepsy." (PMID 41007641, 2025). "However, as our sample size was small, we only had a few SCN3A variant-induced epilepsy cases, and additional in-depth study is thus required." (PMID 38174099, 2023). "Furthermore, the rs13405797 of SCN1A and rs2119067 of SCN3A can be considered as epilepsy risk biomarkers within individuals have a family history of epilepsy." (PMID 35801810, 2022). "They reported that loss-of-function mutation in SCN3A, reduced trafficking of channel proteins or down regulated expression may result in epilepsy." (PMID 33841294, 2021). "Apart from de novo mutations, inherited mutations are known to cause SCN3A-seizure disorders." (PMID 33841294, 2021). "Regions of SCN3A with functionally validated epilepsy variants with references." (PMID 33841294, 2021). "Microduplication mutations have likewise been implicated as epilepsy-related SCN3A mutations." (PMID 33841294, 2021). "SCN3A codes for a voltage-gated sodium channel and generates and propagates action potential in neurons and muscle and has recently been reported to be associated with epilepsy which is a reported comorbidity of Parkinson's disease (PD)." (PMID 31487305, 2019). "Abnormalities were most frequent in the SCN2A (70.6%) group, followed by the SCN8A (42.9%) and SCN1A (31.6%) groups; one patient with SCN3A-related epilepsy also exhibited abnormal findings." (PMID 41573391, 2025). "Its involvement in epilepsy is supported by studies that have shown that the SCN3A mRNA is highly expressed in CA4 hilar cells within the epileptic hippocampus." (PMID 41007641, 2025). "Mutations in several NaV-α subunits were associated with epilepsy, including NaV1.1 (SCN1A), NaV1.2 (SCN2A), NaV1.3 (SCN3A), NaV1.6 (SCN8A), and NaV1.7 (SCN9A)." (PMID 39728106, 2024).
epilepsy (continued). "In fact, pathogenic variants of SCN1A/NaV1.1, SCN2A/NaV1.1, SCN3A/NaV1.1, SCN8A/NaV1.6, and SCN1B/β1, which are expressed in the central nervous system, are important causes of different types of epilepsies, including mild and severe forms." (PMID 37654020, 2024). "Genetic variants of NaV1.1 (SCN1A), NaV1.2 (SCN2A), NaV1.3 (SCN3A), and NaV1.6 (SCN8A) sodium channels are involved in a broad spectrum of diseases, including several types of epilepsy." (PMID 37654020, 2024). "In the wide spectrum of the hundreds of epileptogenic genes, SCN1A and 2A are the most relevant, but also SCN3A and 8A have been found to be correlated with forms of epilepsy." (PMID 37240836, 2023). "Nav channel mutations are related to epilepsy, including α subunits, such as Nav1.1 (SCN1A), Nav1.2 (SCN2A), Nav1.3 (SCN3A), Nav1.6 (SCN8A), and Nav1.7 (SCN9A), and the β subunit (SCN1B)." (PMID 38174099, 2023). "Developmental and epileptic encephalopathy 62 (MIM #617938) and epilepsy, familial focal, with variable foci 4 (MIM #617935), are caused by a heterozygous mutation in the SCN3A gene." (PMID 37405542, 2023). "SCN1A, SCN2A, SCN3A, SCN8A, SCN9A, SCN11A, and SCN1B sodium channel gene mutations were intimately associated with epilepsy and displayed significant heterogeneity in pathogenesis and clinical symptoms." (PMID 38174099, 2023). "The rs13405797 of SCN1A and rs2119067 of SCN3A were related to family history of epilepsy (p = 0.035 and 0.023)." (PMID 35801810, 2022). "VGSCs are known to play an important role in neuronal excitability and epilepsies; especially mutations in VGSC subunit genes such as SCN1A, SCN2A, SCN3A, and SCN8A have been found to cause human epilepsies." (PMID 35860491, 2022). "Voltage-gated sodium channels (VGSCs) play a critical role in generation of action potentials, SCN1A, SCN2A, SCN3A, SCN8A and SCN1B have been identified to be associated with a spectrum of epilepsy phenotypes and neurodevelopmental disorders." (PMID 36006933, 2022). "This study investigated several genetic variants of SCN genes (SCN1A, SCN2A, SCN3A, SCN1B, SCN2B, SCN3B and SCN8A) and their association with epilepsy risk; these genes have been studied in this regard and conflicted results were reported." (PMID 35801810, 2022). "Genetic variants in the voltage-gated sodium channels SCN1A, SCN2A, SCN3A, and SCN8A are leading causes of epilepsy, developmental delay, and autism spectrum disorder." (PMID 34425903, 2021). "SCN1A, SCN2A, SCN3A, and SCN8A genes which individually encode voltage-gated sodium channels, that is NaV1.1, NaV1.2, NaV1.3, and NaV1.6, are related to early onset epilepsies." (PMID 34276290, 2021). "Advanced search was done using the following keyword combinations: SCN1A mutations in epilepsy, SCN1B mutations in epilepsy, SCN2A mutations in epilepsy, SCN3A mutations in epilepsy, SCN8A mutations in epilepsy and functional studies of VGSCs in epilepsy." (PMID 33841294, 2021). "The Chr2q24 linked region encompassed ~65 genes including the known epilepsy gene cluster (SCN1A, SCN2A and SCN3A)." (PMID 33216760, 2020). "Looking into the DEG subnetwork, we found that some well-known ASD candidate genes, such as Kcnma1, Shank2, Cacna1a and Cacna1b, and epilepsy candidate genes, such as Scn3a, Grin2a, Gabrg2, and Grin2b, are hub genes in this subnetwork." (PMID 32033586, 2020). "Five different genes that encode alpha subunits of sodium ion channels have been reported to have mutations that lead to epilepsy; these include SCN1A, SCN2A, SCN3A, SCN8A, and SCN9A, and epilepsy-inducing mutations have also been reported in SCN1B." (PMID 33102526, 2020). "NaV1.1 (SCN1A), NaV1.2 (SCN2A), NaV1.3 (SCN3A), NaV1.6 (SCN8A) and NaV1.7 (SCN9A) are genes whose mutations are related to epilepsy." (PMID 33013363, 2020). "SCN3A gene has an acknowledged role in the epilepsy and hsa-miR-106a-5p participates in the pathogenesis of Alzheimer's disease." (PMID 31709263, 2019).
epilepsy (continued). "So, the HOXA-AS2/ hsa-miR-106a-5p/ SCN3A axis is a putative target for future functional studies in epilepsy and a possible therapeutic target in this regard." (PMID 31709263, 2019). "Biological prioritization implicates SCN1A, SCN2A, SCN3A, and TTC21B as the most likely genes underlying the signal at 2q24.3 for all epilepsy, focal epilepsy and genetic generalized epilepsy." (PMID 30531953, 2018). "Now, only 2 genes, SCN1A and SCN3A remain in the list both of which are excellent candidates for an epilepsy phenotype." (PMID 19057649, 2008). "One patient with SCN3A-related epilepsy exhibited vascular abnormalities." (PMID 41573391, 2025). "Since up-regulation of SCN3A has been demonstrated to enhance neuronal excitability and contribute to the development of epilepsy, the reduction of SCN3A expression by VPA due to its promotion on methylation may underlie the anti-epileptic effect of VPA." (PMID 39563472, 2024). "Further, de novo SCN3A that are both GOF and LOF have been implicated in childhood epilepsies." (PMID 35689251, 2022). "At present, voltage-gated sodium channel genes such as SCN1A, SCN2A, SCN3A, and SCN8A were reported to be causative genes of epilepsy, among them SCN2A has been reported to be the second most common, next only to SCN1A, the first reported causative gene for epilepsy." (PMID 35431799, 2022). "After searching in DrugBank, we retrieved a total of 47 anti-epileptic drugs and 151 targets, of which identified 17 target genes (CACNA1A, CHRNA4,CHRNA7,GABRA1,GABRA2,GABRB2,GABRG2,GRIK1,GRIN1,GRIN2B,KCNQ2,KCNQ3,SCN1A,SCN2A, SCN3A,SCN8A and SCN9A) were overlapped with risk genes of epilepsy." (PMID 36006933, 2022). "Using targeted exome sequencing including 412 epilepsy genes in 63 patients and their families, an inherited missense mutation p.(R621C) was identified in SCN3A but no functional studies was done." (PMID 33841294, 2021). "Similarly, SCN3A, an epilepsy gene was picked up by MAPSD in neuronal cells in the cerebral cortex and hippocampus." (PMID 32984858, 2020). "SCN3A-related epilepsies identified in clinical patients through WES and/or NGS." (PMID 33013363, 2020). "Notably SCN3A was selected by a team of biochemical geneticists specifically with respect to the epilepsy presented by the child." (PMID 28539120, 2017). "Functional studies are underway to further investigate the role of SCN3A in epilepsy." (PMID 28539120, 2017). "In this single-center cohort of 139 pediatric patients with genetically confirmed SCN1A-, SCN2A-, SCN3A-, and SCN8A-related epilepsies, structural brain MRI abnormalities were identified in 37.4% of the patients." (PMID 41573391, 2025). "To address this gap, we analyzed structural brain MRI findings in a large single-center pediatric cohort with genetically confirmed SCN1A-, SCN2A-, SCN3A-, and SCN8A-related epilepsy." (PMID 41573391, 2025). "This study is one of the largest single-center comparative neuroimaging analyses of SCN1A-, SCN2A-, SCN3A-, and SCN8A-related epilepsies." (PMID 41573391, 2025). "Abnormal MRI findings have also been reported in SCN2A, SCN3A, and SCN8A-related epilepsies, although most studies to date have been limited to case reports or small series, and imaging patterns remain poorly defined across genotypes." (PMID 41573391, 2025). "Mutations in four evolutionary and functionally similar α subunit genes, SCN1A, SCN2A, SCN3A, and SCN8A, lead to neurological diseases, including various types of epilepsy." (PMID 41007641, 2025). "Of these, 114, 17, 1, and 7 patients had SCN1A-, SCN2A-, SCN3A-, and SCN8A-related epilepsy, respectively." (PMID 41573391, 2025). "Increases in genetic testing have prompted numerous reports identifying four VGSC genes of significant clinical importance in epilepsy: SCN1A, SCN2A, SCN3A, and SCN8A." (PMID 41007641, 2025). "SCN2A, SCN3A, and SCN3B were upregulated in neurons, described to be involved in neuronal excitation and epilepsy pathogenesis." (PMID 23690787, 2013).
epilepsy (continued). "Pathogenic variants in this gene lead to a spectrum of neurodevelopmental conditions including epilepsy, as well as developmental brain malformations but, to our knowledge, no PTVs in SCN3A have been previously reported in ASD individuals." (PMID 38519481, 2024). "For SCN3A, rs16850186 and the rs72550243 of SCN1B, we declare them as genetics factors that may influence the development and progression of epilepsy in Saudi population." (PMID 35801810, 2022). "There is a lack of clinical data on SCN3A-related epilepsies, especially regarding treatment and the use of specific medication." (PMID 33013363, 2020). "SCN9A is unlike the epilepsy-related VGSC-α subunit molecules SCN1A, SCN2A, SCN3A and SCN8A each of which is expressed primarily in brain, whereas SCN9A is expressed primarily in peripheral nerves." (PMID 33216760, 2020).
Epileptic encephalopathy (7 papers, 2018 to 2025). A condition in which epileptiform abnormalities are believed to contribute to the progressive disturbance in cerebral function. "Several reports have described SCN2A-related epileptic encephalopathy with severe cortical dysplasia and opercular malformation detected on MRI, as well as SCN3A variants linked to extensive cortical folding abnormalities." (PMID 41573391, 2025). "Among them are SCN2A or SCN3A, sodium channel encoding genes, strongly associated with epileptic encephalopathy." (PMID 33126574, 2020). "Mutations in SCN2A and more recently SCN3A are established monogenic causes of epileptic encephalopathy that, like SCN1A, cause dysfunction of the encoded ion-channels, which is believed to disturb the fine balance between neuronal excitation and inhibition." (PMID 30531953, 2018). "It was reported that SCN3A mutations cause early infantile epileptic encephalopathy." (PMID 37684436, 2023). "Both deletions and duplications, involving each of SCN1A, SCN2A, and SCN3A, have been presented previously in cases with severe epileptic encephalopathies and developmental delay." (PMID 31694722, 2019). "In addition, mutations in SCN2A also cause epileptic encephalopathy (MIM 613721) and missense variants in SCN3A have been implicated in focal epilepsy in children." (PMID 31694722, 2019).
polymicrogyria (7 papers, 2020 to 2025). A developmental brain abnormality characterized by an excessive amount of small convolutions on the surface of the brain and cognitive dysfunction. "Local thinning of the cortex generated many small, tightly packed folds, resembling polymicrogyria, a condition linked to mutations such as those affecting the gene SCN3A, which encodes instructions to form a sodium channel." (PMID 41459648, 2025). "Epileptic encephalopathy and polymicrogyria are the main features related with these pathogenic variants, and, so far, polymicrogyria was not reported in other channelopathies, being an exclusive characteristic of SCN3A mutants." (PMID 33013363, 2020). "In addition to detecting pathogenic variants in genes previously linked to polymicrogyria (eg, ADGRG1/GPR56, SCN3A, TUBB2B), we discovered 6 genes linked to polymicrogyria for the first time (QRICH1, TMEM161B, PANX1, KIF26A, SCN2A, and MAN2C1)." (PMID 37486637, 2023).
focal epilepsies (5 papers, 2015 to 2022). "An SCN3A mutation with increased persistent current was identified in a child with pediatric partial epilepsy." (PMID 26029160, 2015). "Point mutations in SCN3A genes have been reported in patients with focal epilepsies." (PMID 33841294, 2021).